LAG3 (lymphocyte activating 3)
Diseases named in the same sentence as LAG3 in open-access papers (continued):
Sharing a sentence is not in itself a finding about the gene and the disease.
celiac disease (1 paper, 2022). An autoimmune genetic disorder with an unknown pattern of inheritance that primarily affects the digestive tract. "A direct comparison of the gene expression of LAG3 between celiac disease and control was statistically significant: 30.7 ± 17.9 vs. 4.6 ± 4.9 (p < 0.001)." (PMID 36011206, 2022). "Despite the fact that the external and internal histological controls were positive, no staining of LAG3 was found in the lamina propria of celiac disease cases." (PMID 36011206, 2022).
chondrosarcoma (1 paper, 2022). A malignant cartilaginous matrix-producing mesenchymal neoplasm arising from the bone and soft tissue. "In this study, increased expressions of lymphocyte activation gene-3 (LAG3), T cell immunoglobulin mucin (TIM3), B7 superfamily member-H3 (B7H3), signal regulatory protein alpha (SIRPA), and colony-stimulating factor 1 receptor (CSF1R) were observed in chondrosarcoma." (PMID 35163019, 2022).
choriocarcinoma (1 paper, 2023). An aggressive malignant tumor arising from trophoblastic cells. "In addition, the expression density of LAG-3 in the TIIs of choriocarcinoma and PSTT was higher than that in ETT." (PMID 36875956, 2023). "Moreover, the expression of LAG-3 in the TIIs of choriocarcinoma and PSTT was higher than that in ETT." (PMID 36875956, 2023).
chronic GvHD (1 paper, 2023). "The incidence of chronic GvHD was similar between the LAG3 rs870849 genetic groups (CC 36.8%; CT 42.7%; TT: 40.2%: p: 0.402)." (PMID 36742309, 2023).
chronic myelogenous leukemia (1 paper, 2022). "In patients with chronic myelogenous leukemia, Jani-Sofia Almeida observed significant alterations on the expression of tumor recognition (NCRsandNKp80) and immune regulatory receptors (LAG-3, TIM-3, and CD137) by NKT-like cells." (PMID 35783158, 2022).
chronic osteomyelitis (1 paper, 2019). "Indeed, an increased expression of LAG-3 was found on T cells in blood samples of patients suffering from chronic osteomyelitis and was associated with impaired T cell proliferation and function." (PMID 31396229, 2019).
Cognitive impairment (1 paper, 2023). Abnormal cognition is characterized by deficits in thinking, reasoning, or remembering. "As shown by these results, deletion of endothelial cell‐specific Lag3 in C57BL/6 mice can reverse α‐Syn PFF‐induced cognitive impairment." (PMID 37381656, 2023). "In conclusion, our study has, for the first time, demonstrated in detail that the effect of α‐Syn PFF‐induced cerebral cerebrovascular injury via Lag3‐dependent endocytosis by BMVECs leads to cognitive impairment, which is independent from neuronal damage." (PMID 37381656, 2023). "As shown in Section 2.9, deletion of Lag3 in ECs in vivo substantially reduces α‐Syn PFF‐induced cerebral microvascular injury and cognitive impairment." (PMID 37381656, 2023).
colonic Crohn’s disease (1 paper, 2020). "It is unknown if mucosal expression of LAG-3 is specific to UC and therefore further studies are planned to explore the expression of LAG-3 in ileal and colonic Crohn’s disease, and potentially in other conditions characterized by localized, immune-mediated inflammation." (PMID 32179884, 2020).
corneal disease (1 paper, 2018). "In this report, we found that LAG-3 is highly expressed on HSV-specific CD8+ T cells from symptomatic (SYMP) individuals, in which HSV-1 reactivation often causes painful recurrent corneal disease." (PMID 30619285, 2018). "In summary, the present study demonstrates, for the first time, that the cornea and TG from HSV-1 infected mice, with UV-B-induced recurrent corneal disease, present more exhausted HSV-specific PD-1+CD8+ T cells and LAG-3+CD8+ T cells." (PMID 30619285, 2018).
dermatitis (1 paper, 2023). An inflammatory process affecting the skin. "Findings of Wang et. al indicated one additional case of dermatitis upon increasing the dose of LAG‐3 inhibitor from 0.5 to 2 mg (mg); however, due to the limited sample size (n = 11), it is difficult to draw any conclusions." (PMID 38047262, 2023).
endotoxemia (1 paper, 2026). "We therefore propose a model in which gut-derived low-grade endotoxemia drives myeloid secretion of Galectin-3, which in turn sustains constitutive LAG3 expression on Treg cells and contributes to Treg cell insufficiency and islet autoimmunity." (PMID 41477833, 2026).
essential tremor (1 paper, 2022). A relatively common disorder characterized by a fairly specific pattern of tremors which are most prominent in the upper extremities and neck, inducing titubations of the head. "A recent study in the Chinese population found that serum LAG3 levels were considerably greater in PD patients than gender- and age-matched controls and patients with essential tremor, suggesting a potential role of LAG3 as a promising molecular biomarker of PD." (PMID 35203580, 2022).
filariasis (1 paper, 2021). "We expanded on this analysis further by simultaneously analyzing these subsets with their expression of Tim-3, LAG-3, PD-1, CD39, and KLRG-1 and building a comprehensive picture of exhausted T cells during filariasis." (PMID 34485170, 2021).
glomerulonephritis (1 paper, 2024). A renal disorder characterized by damage in the glomeruli. "Coexistence of other glomerulonephritis was associated with lower proportion of CD3+ and CD3+ LAG-3+ T cells (p=0.003 and 0.004, respectively)." (PMID 38812511, 2024).
gynecologic cancers (1 paper, 2023). "High levels of IDO1 and LAG3 suggest that clinical trials with IDO1 inhibitors or LAG3 inhibitors, respectively, may be warranted in gynecologic cancers." (PMID 36824739, 2023). "Compared to patients with non-gynecologic cancers, more patients with gynecologic cancers express high levels of IDO-1 (44 vs. 13%, p<0.001), LAG3 (35 vs. 21%, p=0.008) and IL10 (31 vs. 15%, p=0.002)." (PMID 36824739, 2023).
hyperalphalipoproteinemia (1 paper, 2021). An autosomal dominant genetic condition caused by mutation(s) in the CETP gene, encoding cholesteryl ester transfer protein. "In subjects with hyperalphalipoproteinemia (HDL-C ≥ 60 mg/dL), low plasma LAG3 protein levels significantly increased MI risk (odds ratio 1.45) and plasma LAG3 added predictive value to the Framingham risk score." (PMID 33398433, 2021).
Hyperglycemia (1 paper, 2025). An increased concentration of glucose in the blood. "Recent research has demonstrated that hyperglycemia-driven metabolic stress directly impairs immune checkpoint pathways, including PD-1, PD-L1, CTLA-4, TIM-3, and LAG-3, by altering T-cell bioenergetics, mitochondrial function, and redox balance." (PMID 41463504, 2025). "Chronic exposure to hyperglycemia, advanced glycation end products, and pro-inflammatory cytokines may drive TRM exhaustion, marked by upregulation of inhibitory receptors, including PD-1, TIM-3, and LAG-3, thereby weakening protective functions." (PMID 41463504, 2025).
hyperplasia (1 paper, 2023). An abnormal increase in the number of cells in an organ or a tissue with consequent enlargement. "Immunohistochemistry was applied to detect the expression of LAG-3 and PD-1 levels in 137 cases of DLBCL tissues and 20 cases of reactive lymphoid hyperplasia." (PMID 37841254, 2023).
immunotoxicity (1 paper, 2025). "The combination of MSA-2 with anti-PD-1 mAb and anti-LAG-3 mAb showed no signs of severe immunotoxicity in a murine model." (PMID 40796887, 2025).
injury (1 paper, 2017). Damage inflicted on the body as the direct or indirect result of an external force, with or without disruption of structural continuity. "T-cell function was suppressed by elevated LAG-3 expression in patients with active liver injury." (PMID 28072682, 2017).
Insulin resistance (1 paper, 2025). Increased resistance towards insulin, that is, diminished effectiveness of insulin in reducing blood glucose levels. "Furthermore, insulin-specific CD8 T cells from high-H exhibited increased expression of the activation markers CD69 and LAG3 compared to bulk CD8 T cells, but not to low-H individuals, suggesting that their activation is independent from insulin resistance." (PMID 39656436, 2025).
invasive carcinoma (1 paper, 2021). A carcinoma that is not confined to the epithelium, and has spread to the surrounding stroma. "However, S100A8, LAG3, CXCL10, CXCL9 and BIRC5 showed a difference in fold change between DCIS and invasive carcinoma although statistically not significant (adjusted p value > 0.05)." (PMID 34504204, 2021).
juvenile rheumatoid arthritis (1 paper, 2022). "We have reported that LAG-3 could play a role in juvenile rheumatoid arthritis, supporting that LAG-3 could be important for immunoreactions and immune maturation during infancy." (PMID 35784333, 2022).
kidney damage (1 paper, 2025). "Treatment of WT recipients with an antagonistic LAG3 antibody enhanced anti-donor immune responses and induced kidney damage associated with chronic rejection." (PMID 40359031, 2025).
kidney transplant (1 paper, 2022). A surgical procedure in which one or both kidneys from a donor are implanted into a recipient. "Comprehensive sample analysis revealed dysregulation of FGL1/LAG‐3 and PD‐L1/PD‐1 immune checkpoints in allogeneic heart transplantation mice and clinical kidney transplant patients." (PMID 34738731, 2022).
laryngeal carcinoma (1 paper, 2022). Carcinoma that arises from the laryngeal epithelium. "We found that laryngeal cancer samples in the low-risk score group were more sensitive to PDCD1, LAG3, CTLA4, and TIGHT." (PMID 36335208, 2022). "We found that low-risk laryngeal cancer samples were more sensitive to PDCD1, LAG3, CTLA4, and TIGHT, indicating that fatty acid metabolism is of interest in terms of assessing the TME characteristics in patients with laryngeal cancer." (PMID 36335208, 2022).
leukoplakia (1 paper, 2024). A white patch or plaque on a mucous membrane that cannot be characterized clinically or pathologically as any other disease. "Finally, we found that NK/T cell subgroups in the HNSCC group highly expressed marker genes of depleted T cells such as CTLA4, LAG3, TIGIT, and HAVCR2, indicating that the inhibition degree of NK/T cells in the HNSCC group was stronger than that of leukoplakia." (PMID 38582791, 2024).
lung disease (1 paper, 2018). "In the SR-triggered farmer's lung disease model, Foxp3+ CD4+ T cells are the majority of the IL-10-producing LAG3+CD49b+ T cell subset in the lungs, however, there are similar percentages of Foxp3− CD4+ and CD8+ T cells (16% each)." (PMID 30510554, 2018).
lymphedema (1 paper, 2023). Excess fluid collection in tissues, causing swelling. "We next examined the expression patterns of PD-1, Tim-3, Lag-3, and PD1+Tim-3+ on peripheral CD8+ T cells in lymphedema, post-LVA, and HCs." (PMID 37250774, 2023). "Additionally, PD-1, Lag-3, and PD-1+Tim-3+ expression on CD4+ T cells showed a significant upregulation in patients with lymphedema compared to HCs." (PMID 37250774, 2023).
malignant glioma (1 paper, 2019). A grade III or grade IV glioma arising from the central nervous system. "We believe that the low expression of Tim-3 and Lag-3 in the malignant glioma models contributed to the sub-optimal efficacy of the D2C7-IT+αTim-3/αLag-3 therapies." (PMID 31142380, 2019).
medulloblastoma (1 paper, 2023). A malignant, invasive embryonal neoplasm arising from the cerebellum. "Across medulloblastoma samples in Immune Desert, WNT subgroup expressed LAG3 at significantly higher levels compared to SHH and there was a non-significant trend between WNT and Group3/4 (two-sided Student’s t test, p = 0.02 and 0.08)." (PMID 37679810, 2023).
meningioma (1 paper, 2013). A generally slow growing tumor attached to the dura mater. "Most of these genes were lowly expressed in both benign and malignant meningiomas; however, five genes (ADCY3, GAS7, LAG3, LRR32 and SPON2) showed a trend of elevated expression (>3 fold in mean values) in malignant meningiomas." (PMID 23349797, 2013).
metastasis (1 paper, 2023). The spread or migration of cancer cells from one part of the body (where they first appeared) to another. "However, the percentage of LAG-3+ cells was less than 5% in the case of NK cells, which suggests that the NK cells activated by the STING-LNPs had not suppressed the cancer cells via immune checkpoint molecules in Renca lung metastasis." (PMID 38258042, 2023).
metastatic cancers (1 paper, 2022). A carcinoma which has spread from the original site of growth to another anatomic site. "Blocking LAG-3 has been demonstrated to improve cytotoxic T-lymphocyte proliferation, and for this study, a tolerable response was observed as a monotherapy and in combination with anti-PD-1 spartalizumab, highlighting the importance of inhibitor of immune checkpoint therapies in metastatic cancers." (PMID 35625975, 2022).
migraine (1 paper, 2023). "For this purpose, the frequencies of CD4 rs1922452, CD4 rs951818, and LAG3 rs870849 genotypes and allelic variants, using a specific TaqMan-based qPCR assay, were assessed in 290 patients diagnosed with migraine and in 300 healthy controls." (PMID 36674807, 2023). "However, and taking into account this main limitation, this study suggests the absence of association between CD4 rs1922452, CD4 rs951818, and LAG3 rs870849 SNVs and the risk of developing migraine in the Spanish Caucasian population." (PMID 36674807, 2023). "The present study aims to establish whether these three common SNVs in the LAG3 and CD4 genes are associated with the risk for migraine." (PMID 36674807, 2023). "In this study, we investigated the possible association between common variants in the LAG3/CD4 genes (both genes, which are closely related, encode proteins involved in inflammatory and autoimmune responses) in the risk of migraine in a cohort of Caucasian Spanish participants." (PMID 36674807, 2023). "Despite LAG3 and CD4 not having been the matter of study in migraine patients, the possible role of inflammatory factors in migraine, together with the important role of these proteins in the inflammatory and immune response, suggest that LAG3 and CD4 could be interesting as markers of migraine." (PMID 36674807, 2023).
monoclonal gammopathy of undetermined significance (1 paper, 2023). "LAG-3 expression on PCs in active MM (newly diagnosed and relapse refractory MM) was significantly increased compared to monoclonal gammopathy of undetermined significance (MGUS)/ SMM." (PMID 38203720, 2023).
morbid obesity (1 paper, 2023). An excess of body weight, normally defined as an individual with a body mass index greater than 35 or a body weight greater than one hundred percent of ideal body weight. "Additionally, the expression levels of NKG2D, CD11c, and CD223, also known as lymphocyte activation gene-3 (LAG-3), were significantly increased in the CD56dim, CD16+, NKG2D+ subset from patients with morbid obesity compared to the CTRL population." (PMID 37266430, 2023).
myeloid leukemia (1 paper, 2023). A clonal proliferation of myeloid cells and their precursors in the bone marrow, peripheral blood, and spleen. "Co-stimulatory signals from myeloid leukemia cells enhance Th1 cell exhaustion, elevating immune checkpoints such as PD1, TIM-3, LAG-3, and CTLA-4." (PMID 37891580, 2023).
myositis (1 paper, 2024). "Although we did not classify patients with IIM based on specific myositis antibody subtypes to compare levels of exhausted T cells (owing to limited sample size), we observed increased expression of LAG‐3 and TIM‐3 in both CD4+ and CD8+ T cells in IIM." (PMID 39284778, 2024).
neck cancer (1 paper, 2024). "The LAG-3 inhibitor (#0) exhibits the most significant cluster, followed by neck cancer (#1) and low dose (#2)." (PMID 38390331, 2024).
non-small cell lung adenocarcinoma (1 paper, 2025). Type of epithelial lung cancer arising from glandular origin. "In non-small-cell lung adenocarcinomas, elevated levels of LAG-3 have been linked with poorer overall survival." (PMID 40367012, 2025).
onchocerciasis (1 paper, 2018). Onchocerciasis is a form of filariasis, caused by the parasitic worm Onchocerca volvulus, transmitted by the black fly. "In contrast, type 1 regulatory T (Tr1) cells are characterized by the expression of CD49b and LAG3 and the secretion of IL-10 and TGF-β have been shown to be important during onchocerciasis." (PMID 29324739, 2018).
oral squamous cell carcinoma (1 paper, 2024). "AhR also plays a central role in IFNγ-induced expression of IDO1, PD-L1, CTLA-4, LAG-3, and CD39 in an oral squamous cell carcinoma model." (PMID 38632994, 2024).
penile cancer (1 paper, 2025). A primary or metastatic malignant neoplasm that affects the penis. "There are also several other checkpoint molecules that could prove to be important as prognostic and predictive biomarkers in penile cancer, such as CTLA-4, TIM3, and LAG3, molecules that were not included in this study but would be of great interest to investigate." (PMID 40822998, 2025).
penile squamous cell carcinomas (1 paper, 2024). "The number of immune cells expressing the immune checkpoints LAG3, PD1, and TIM3 were significantly more numerous in grade 3 than grade 1 penile squamous cell carcinomas." (PMID 38691575, 2024).
periodontitis (1 paper, 2021). An acute or chronic inflammatory process that affects the tissues that surround and support the teeth. "GCF treatment of CD3+ lymphocytes from the periodontitis patients significantly increased expression of T-cell exhaustion markers TIM-3 and LAG-3." (PMID 34502071, 2021).
peripheral vascular disease (1 paper, 2022). Any disorder affecting blood flow through the veins or arteries outside of the heart. "We identified the LAG3 rs3782735 variant as significantly associated with plasma LAG3 protein levels, and neighboring C1S rs7970720 variant as significantly associated with peripheral vascular disease (ABI) in the MESA population." (PMID 35501457, 2022).
pituitary adenomas (1 paper, 2023). "Other immune checkpoints (such as LAG3) are also potential targets for immunotherapy in aggressive pituitary adenomas/PitNets." (PMID 36658300, 2023). "Preliminary data are available for LAG3: in 12 somatotroph tumors, an increased expression of LAG3 was identified with respect of other pituitary adenomas/PitNets." (PMID 36658300, 2023).
plasma cell dyscrasia (1 paper, 2023). "Therefore, the aim of our study was to assess the possible role of LAG-3 expression on regulatory PCs in patients with plasma cell dyscrasia." (PMID 38203720, 2023).
postweaning multisystemic wasting syndrome (1 paper, 2022). Pig disease caused by porcine circovirus type 2 (PCV2). "An up-regulation of TIM3 and IDO1 has been described in the context of PRRSV- and CSFV-infected pigs, respectively, whereas LAG3 was reported to play a limited role during the pathogenesis of postweaning multisystemic wasting syndrome." (PMID 36713151, 2022).
psoriatic arthritis (1 paper, 2025). Joint inflammation associated with psoriasis. "LAG-3, an immune checkpoint receptor of the immunoglobulin superfamily, has been implicated in self-tolerance, as evidenced by studies showing reduced LAG-3+CD4+ T cells in patients with active psoriatic arthritis." (PMID 41023624, 2025).
rectal tumor (1 paper, 2024). "In our study, FOXP3(r = 0.179), CD72(r = 0.155), RUNX1(r = 0.327), LAG3(r = 0.194), CTLA4(r = 0.236) have a positive correlation with AP3M2 in Colon Neoplasm, but no irrelevancy in rectal tumor." (PMID 38177168, 2024).
rectum adenocarcinoma (1 paper, 2019). An adenocarcinoma arising from the rectum. "However, we found a higher level of PD-L1, PD-L2, CD80, CD86, Tim-3, LAG3, and 4-1BB in EBV-positive STAD and cytomegalovirus-positive colon and rectum adenocarcinoma than in virus-negative tumor samples." (PMID 30911684, 2019).